IL10 (interleukin 10)
Diseases named in the same sentence as IL10 in open-access papers (continued):
Sharing a sentence is not in itself a finding about the gene and the disease.
colitis (continued). "That population is considered resident and is characterized by the production of anti-inflammatory cytokines such as IL-10 and TGF-β and is important in the suppression of experimental DSS colitis (together with the resident mucosal dendritic cells)." (PMID 36792680, 2023). "The anti-inflammatory factors that we detected in the serum and tissue of colitis mice included TGF-β and IL-10, the two major cytokines secreted by alternatively activated macrophages (M2 macrophages)." (PMID 36979804, 2023). "For instance, cystatin produced by Acanthocheilonema viteae can stimulate macrophages to produce a considerable amount of IL-10, which reduces clinical damage in mouse models of OVA-induced allergic asthma and DSS-induced colitis." (PMID 38152266, 2023). "At day 3, IL-10 and IL-19 expression levels were increased in S.C./pLJD-CMV-mIL19-treated DSS colitis mice compared to control mice, as determined by RT-PCR." (PMID 37375032, 2023). "Loading TNF-α with GELNs can downregulate NLRP3, caspase-1, IL-1β, TNF-α, IL-6 and IL-1b, upregulate anti-inflammatory substances such as IL-10 and IL-22 in colon tissue of DSS-induced colitis mice." (PMID 37033644, 2023). "Regarding the DSS-colitis therapeutic design, BLI showed a moderate positive correlation with Il6, while Tgfb1 and the Il10/Il1b1, Il10/Il6, Tgfb1/Il1b1, Tgfb1/Il6, and Tgfb1/Tnfa ratios correlated in the opposite way." (PMID 37047397, 2023). "To determine if ALDH1A inhibition suppresses colitis in another mouse model of IBD with a different mechanism of disease development, we tested the efficacy of WIN 18,446 in Il10−/− mice using the same study design as Mdr1a−/− mice." (PMID 37764666, 2023). "In this study, we showed that IL-19 was an IL-10 inducer and that IL-10 production was stimulated at the early stage of DSS-induced colitis." (PMID 37375032, 2023). "According to previous studies, recombinant interleukin (IL)-10 protein and genetically modified bacteria secreting IL-10 ameliorate dextran sulfate sodium (DSS)-induced colitis in mice." (PMID 37375032, 2023). "Subsequently, PEP-1 was further evaluated in two in vivo experimental colitis models (chemically induced by DNBS administration and spontaneous colitis induced in IL-10 knock-out (KO) mice (to assess its effectiveness in counteracting inflammation." (PMID 37759516, 2023). "Nociceptive behaviors have been previously observed to occur at the peak of colitis in both DSS-treated and IL-10 KO mice." (PMID 37049400, 2023). "Currently, the sex differences in the phenotype of IL-10−/− mice remain unexplored, which represents an important gap in our understanding of this IBD model and its implications for colitis research." (PMID 37373511, 2023). "To further confirmed this, we established experimental colitis models in wild-type (WT) C57BL/6 mice using TNBS and DSS and generated IL-10 KO mice." (PMID 37124046, 2023). "The significant increase in nicotinic acid in the B. coagulans intake group suggests that B. coagulans induces the differentiation of regulatory T cells, resulting in an increase in IL-10 and TGF-b, thus exhibiting an inhibitory effect on colitis." (PMID 37873804, 2023). "Recent study in a TNBS-induced colitis mice model, human UC-MSCs transplantation protected against experimental colitis by promoting CD5 + B cells and IL-10-secreting CD5 + regulatory B cells (Bregs)." (PMID 36707899, 2023). "In this report, we determined if inhibiting RA synthesis can be efficacious in reducing colitis arising from different etiologies by utilizing two additional models of IBD, Il10−/− and Mdr1a−/− mice." (PMID 37764666, 2023). "DPA attenuates inflammation in DSS-induced colitis model; modulates pro-inflammatory cytokines (TNF-α, IL-1β, IL-6) and anti-inflammatory cytokine (IL-10); inhibits synthesis of pro-inflammatory eicosanoids (PGE2, LTB4)." (PMID 37868958, 2023).
colitis (continued). "On the other hand, an experimental study that induced acute colitis with 2.5% DSS for 5 days observed increased TNF-α levels and maintenance of IL-10 levels of the livers of these animals." (PMID 37577725, 2023). "Similar results are observed in a separate report, in which Odoribacter splanchnicus colonization leads to an increase in Foxp3+/RORγt+ Treg cells, induction of IL-10, and production of SCFA, thus reducing colitis in mouse models." (PMID 35967333, 2022). "To know the reason for the amelioration of colitis severity in BALB/c, we checked the expression of one of the most crucial anti-inflammatory mediators, IL10." (PMID 35263357, 2022). "In the dextran sodium sulfate (DSS)-induced colitis mouse model, FMT reduces colonic inflammation and improves mucosal immune health by inducing IL-10 expressing CD4+ T cells and invariant NK T cells in the colon of mice." (PMID 36713364, 2022). "Another future direction is therefore to amplify the capacity of this method by incorporating other colitis models within training, such as the 2,4,6-Trinitrobenzenesulfonic acid (TNBS), IL-10 knockout, adoptive cell transfer, and oxazolone models." (PMID 36037173, 2022). "Il10−/− mice, however, were strongly protected from AIEC-induced exacerbated colitis even though we only detected anti-Ent antibodies (despite lower titers compared to Lcn2−/− and WT mice), but no measurable anti-GlcEnt antibodies." (PMID 36094114, 2022). "Chlorogenic acid and gallic acid have been found to have identical efficiencies in the alleviation of interleukin-10 knockout IBD, as well as colitis induced by TNBS, 1, 2-Dimethylhydrazine (DMH), or DSS." (PMID 36558542, 2022). "Intestinal DCs and monocytes tend to produce more IL-10, suggesting that FMT inhibits colitis by downregulating antigen presentation and promoting the production of IL-10." (PMID 35734396, 2022). "In summary, our study demonstrated that exposure to heavy-ion radiation (28Si or 56Fe) is associated with a greater incidence of colonic inflammation, colitis, and CAC in Il10-/- mice." (PMID 36584137, 2022). "The pharmacological evaluation showed that FMPs attenuated inflammation in AA-induced colitis by reducing the serum concentrations of TNF-α, IL-6, IL-8, and IL-10 and the colonic concentrations of MPO, MMP9, and CXCR1." (PMID 35620404, 2022). "Tr1 cells were highly suppressive through secretion of IL-10 and TGF-β, and they suppressed colitis in a mouse T-cell transfer model." (PMID 36389662, 2022). "Fermented soy gram, consisting of isoflavones, down-regulated IL-1β and up-regulated IL-10; hence, the permeability of intestinal cells decreased in TNBS-induced colitis." (PMID 35566252, 2022). "In a comorbid mice model of neonatal maternal separation (NMS) stress and colitis, the researchers have explored that NMS stress exacerbates colitis in IL10-/- mice by disrupting intestinal barrier." (PMID 36275694, 2022). "In summary, IR-induced colitis and CAC incidence in Il10-/- mice depends on radiation quality and display co-activation of β-catenin and NF-κB signaling." (PMID 36584137, 2022). "Clostridium butyricum triggers IL-10 production from intestinal macrophages via the TLR2/MyD88 signaling pathway and prevents mice from DSS-induced colitis." (PMID 35967333, 2022). "Additionally, another survey performed in the situation of DSS-induced colitis showed that in vitro presence of chemerin made it impossible for macrophages to create an anti-inflammatory phenotype, which led to a deteriorated expression of arginase-1 and IL-10." (PMID 36235636, 2022). "The results showed that the TNBS group had lower TGF-β1 concentration than the control, however, concentrations of IL-10 and TGF-β1 were significantly elevated with pre-exposure of S. japonicum eggs in the colitis mice." (PMID 36304936, 2022).
colitis (continued). "Similar protective effects against LPS-induced colitis were also observed; IPA protects LPS-induced mice by activating AhR to promote IL-10 production while suppressing the gene expression of TNF-α." (PMID 36159803, 2022). "L. salivarius Ls33 peptidoglycan induced anti-inflammatory IL-10 production, and stimulated Treg responses via NOD2 rescuing symptoms in a tri-nitrobenzene sulfonic acid (TNBS) -induced colitis murine model." (PMID 35464397, 2022). "PSA-induced IL-10 production inhibits the activity of mucosal effector T cells, particularly TH17 cells, and thus protects mice in colitis models." (PMID 36590401, 2022). "Network of cytokines including IL-1β, TNF-α, IL-6, IL-10, IFN-γ, and IL-18, have been reported to regulate mucosal inflammation in colitis, and IL-6, TNF-α are viewed as therapeutic targets in IBD." (PMID 35330829, 2022). "Under host inflammatory conditions, the mono-colonization of Escherichia coli promotes colitis in Il10−/− mice and invasive carcinoma in azoxymethane (AOM)-treated Il10−/− mice." (PMID 35967333, 2022). "Intriguingly, SPH treatment prevented a significant increase in pro-inflammatory TNF-α and IL-6 and additionally augmented the production of anti-inflammatory IL-10 and TGF-β1 compared with the other two colitis groups (p < 0.01)." (PMID 36139127, 2022). "Exosomes derived from bone marrow DCs treated with IL-10 inhibited the expression of the proinflammatory cytokines IL-2, IFN-γ and TNF-α and trinitrobenzene sulfonate-induced colitis." (PMID 36045437, 2022). "Histopathological and molecular analysis of IR-induced colitis and CAC in Il10-/- mice displayed a dependence on radiation quality with the highest effect after 28Si irradiation (LET 69 keV/micron)." (PMID 36584137, 2022). "In colitis induced by exposure to a low dose of DSS, Il10-/-Gpr183-/- animals had less severe inflammation compared to Il10-/- controls." (PMID 36389671, 2022). "IL-10 and LCN2 double-knockout mice have more severe colitis and a higher expression of inflammatory factors." (PMID 36591221, 2022). "The maximum inflammatory response was found in the DSS-induced colitis model, as shown by higher detected levels (p < 0.05) of IL-6, TNF-α, IFN-γ, and IL-10 cytokines." (PMID 35884960, 2022). "Results showed that Shikonin dose-dependently alleviated mice colitis, down-regulated expression of F4/80, iNOS and CD86, decreased IFN-γ, IL-1β, IL-6 and TNF-α, while increased IL-10 in mice colon." (PMID 36059938, 2022). "Intraperitoneal injection of HdAg (H. diminuta antigen) suppressed DSS-induced colitis and reduced IFN-γ, IL-17, TNF-α production and increased IL-10 concentration." (PMID 36558772, 2022). "The administration of IL-10 to CD19−/− mice significantly decreased intestinal damage and adoptive transfer of B10 cells to CD19−/− mice significantly reduced colitis." (PMID 35672305, 2022). "It was remarkable that rats that suffered from DSS-induced colitis had the highest expression levels of pro-inflammatory cytokines IL-6, IL-1β and TNF-α and anti-inflammatory IL-10 levels." (PMID 35745756, 2022). "Meanwhile, it has been suggested that IL-22 exhibited protective ability in regulation of gut inflammation by stimulating colon epithelial cell lines to produce IL-10 and SOCS3 to ameliorate DSS-induced colitis via upregulating claudin-2 expression." (PMID 36092152, 2022). "Other studies pointed out that F.prausnitzii A2-165 attenuates mice colitis induced by 2,4,6-trinitrobenzene sulfonic acid (TNBS) or dinitrobenzene sulfonic acid (DNBS) and modulates the T cell response via inducing IL-10 in human and murine dendritic cells." (PMID 36389768, 2022). "IL-10 produced by intestinal CD4+ T cells is responsible for maintaining immune homeostasis, thereby inhibiting colitis development." (PMID 36590200, 2022). "Foxp3 is involved in the development of Treg cells that secrete IL-10 to inhibit inflammation, and DSS-induced colitis results in a decrease in Foxp3+Treg cells." (PMID 35237276, 2022).
colitis (continued). "For instance, Clostridium butyricum directly triggered IL-10 production by intestinal macrophages in inflamed mucosa via the TLR2/MyD88 pathway, thereby preventing experimental colitis in mice." (PMID 35241180, 2022). "The results presented in this study showed that the level of anti-inflammatory cytokines IL-10 and TGF-β1 decreased in the Colitis and Colitis/CP groups, while SPH treatment elevated the levels of IL-10 and TGF-β1 compared with the control peptide." (PMID 36139127, 2022). "The study indicated that, a large number of proinflammatory factors (IFN-γ, IL-1β, IL-6, and TNF-α) were produced in the serum and colonic tissues after colitis was induced by DSS in mice, while the anti-inflammatory factors (IL-10 and IL-4) decreased." (PMID 36159803, 2022). "To further estimate the influence of MOP upon inflammation in colitis, we detected the levels of TNF-α, IL-1β, IL-6, and IL-10 in the serum from the control, DSS, and DSS + H MOP groups." (PMID 35911761, 2022). "Similar results were reported that when blocking TGF-β or IL-10, peritoneal cell-mediated colitis improvements were lost, confirming the important role of TGF-β or IL-10 in peritoneal cells to exert their therapeutic effects." (PMID 35371051, 2022). "At least seven peptides of the protein MAM induced in vitro production of IL-10 and blocked the development of DSS-induced colitis in mice in vivo." (PMID 35336884, 2022). "On the contrary, the expression of anti-inflammatory factors IL-4, IL-10, TGF-β and Foxp3 were significantly declined in the colitis group compared to the healthy mice." (PMID 35372817, 2022). "Treatment with CM in TNBS-induced colitis in rats also resulted in a reduced levels of colonic TNF-α and IL-10." (PMID 35493477, 2022). "B. vulgatus 7K1 ameliorated DSS-induced colitis in mice by decreasing the concentrations of TNF-α and IL-6 and increasing the production of IL-10 in mouse colon tissues." (PMID 36531989, 2022). "As expected, colitis mice treated with Bp7 and Bp8 exhibited lower concentrations of TNF-α and IL-1β (p < 0.05) and higher concentrations of IL-10 and IL-22 relative to the DSS group (p < 0.05)." (PMID 35681301, 2022). "In agreement with FISH analyses from the DSS colitis model experiments, AIEC was frequently found near or attaching to the intestinal epithelial layer in CTB-immunized control Il10−/− mice." (PMID 36094114, 2022). "Another study showed oral administration of ginger-derived nanoparticles downregulated the pro-inflammatory cytokines (TNF-α, IL-6 and IL-1β), and upregulated anti-inflammatory cytokines (IL-10 and IL-22) in the DSS-induced colitis model." (PMID 35883674, 2022). "The conventionally housed Il-10−/− mice develop spontaneous colitis, and this spontaneous model can better model human IBD compared with the piroxicam-induced colitis model in SPF Il-10−/− mice." (PMID 35013263, 2022). "B. adolescentis IF1-03 has been shown to stimulate maturation of macrophages, producing higher levels of IL-10 and lower levels of IL-6 and TGF-β, features consistent with the upregulation of Treg cells in DSS-colitis mice in vivo and splenocytes in vitro." (PMID 33679767, 2021). "The colitis model group expressed significantly higher levels of colonic TNF-α, IL-1β, and IL-6, and lower levels of IL-10 compared with the control group." (PMID 35071260, 2021). "For example, in dextran sulphate sodium (DSS) colitis, FXR activation via OCA decreases local IL1β and increases systemic IL10 expression." (PMID 34831429, 2021). "A recent study reported that pentanoate enhanced IL-10 secretion in Bregs in a manner dependent on glycolysis and p38 MAPK activity, and pentanoate-treated Bregs protect mice from experimental colitis and multiple sclerosis." (PMID 34099635, 2021). "In contrast, gavage with Kae strongly inhibited the transcription of genes involved in colitis, while reversing the effects of DSS on IL-10 transcription (P < 0.05)." (PMID 34367139, 2021).
colitis (continued). "Olaparib reduced the inflammation score, the concentration of IL-1β and IL-6, enhanced the level of IL-10, and decreased the intestinal permeability in TNBS-colitis." (PMID 34567413, 2021). "Our studies also showed that AS-IV attenuated the DAI and MPO activity, downregulate the expression of Tnf-α and Il-1β and increase the level of Il-10 and Tgf-β in a dose-dependently manner in DSS-induced colitis mice." (PMID 34589089, 2021). "In a T cell–mediated colitis mice model, oral administration of IPyA, a microbiota-derived AHR agonist, decreases the frequency of IFN-γ+ IL-10- CD4+ T cells and increases that of IFN-γ- IL-10+ CD4+ T cells in the colon lamina propria." (PMID 34966278, 2021). "In the E. faecalis-triggered IL10 knockout model of CRC, liposome-encapsulated clodronate selectively reduced colon macrophages, and prevented colitis and CRC." (PMID 33969420, 2021). "In colitis, MSCs are reported to regulate the polarization of M1 to M2 cells in a CCL2-dependent manner by upregulating the expression of IL-10 to alleviate intestinal inflammation." (PMID 34249933, 2021). "Intraperitoneal injection of LPS induced colitis: it induced colon shortening, IL-1β, IL-6, and TNF-α expression and suppressed IL-10 expression in the colon." (PMID 33985438, 2021). "We investigated the role of Foxp3, IL-10, and TGF-β in the suppression of colitis by epicutaneous immunotherapy (ET)." (PMID 33717186, 2021). "In comparison to IL-10 and IL-22, we observed that IL-6 was the most abundantly produced cytokine during DSS-induced colitis development in wild-type mice as well as in mice with reduced STAT3 activity." (PMID 33673239, 2021). "The SCFAs can also regulate the interactions between microbiota and immune cells with the mechanism of stimulating the IL-10 producing Foxp3+ Tregs via inhibiting HDAC, thereby alleviating colitis." (PMID 34917080, 2021). "In contrast to the chronic Il10-deficient model, we observed a sevenfold increase in colon Il33 expression in acute colitis induced by epithelial injury from DSS compared to untreated WT mice, indicating that factors specific to DSS colitis may be regulating IL-33." (PMID 33953267, 2021). "SCFAs also promote the generation of IL-10 in T cells of patients with IBD and the oral administration of SCFAs in mice can alleviate colitis." (PMID 34884466, 2021). "It is reported that the tea extracts significantly decreased the production of proinflammatory cytokines (IL-6 and tumor necrosis factor-α (TNF-α))and increased the anti-inflammatory IL-10 in RAW264.7 macrophages and colitis mice." (PMID 34439208, 2021). "In contrast to skin and liver, where macrophages are not altered, we observed increased levels of macrophages in the colon of PTPN2fl/flxCD11cCre mice, as well as slightly increased mRNA levels of IL-10 in acute DSS and T cell transfer colitis." (PMID 34201918, 2021). "We showed that translocated A. pulmonis into mAT exhibited an ability to induce experimental colitis in both DSS and Il10−/− mouse models." (PMID 34814945, 2021). "In addition, IL-10 plays an effective role in inhibiting inflammation and pathogen clearance during Borrelia recurrentis infection, and L. lactis producing IL-10 could be a therapy of murine colitis." (PMID 34646877, 2021). "NLRP3(−/−) mice exhibited resistance to colon mucosal damage and relieved colitis in the DSS or TNBS (2,4,6-trinitrobenzene sulfonic acid) model, and IL-10(−/−) model, with reduced mortality." (PMID 34294138, 2021). "In colitis induced by the TNBS model, EA decreased MPO activity, IL-1β concentration, iNOS expression, and MDA concentration but increased IL-10 concentration in intestine tissues." (PMID 35095910, 2021). "And, ovalbumin (OVA) induced Tregs from DO11.10 mice prevented colitis together with increased TGF-β and IL-10 secretion in SCID-bg mice." (PMID 34440615, 2021).